MTOR (mechanistic target of rapamycin kinase)
Diseases named in the same sentence as MTOR in open-access papers (continued):
Sharing a sentence is not in itself a finding about the gene and the disease.
cardiac hypertrophy (continued). "To determine the molecular mechanisms through which EGCG attenuates cardiac hypertrophy and myocardial fibrosis, we examined the involvement of the AKT/mTOR signalling pathway under pressure overload-induced injury." (PMID 34607503, 2021). "AKT is a key regulator of cell growth and generally works with several downstream effectors such as mammalian target of rapamycin (mTOR), GSK-3β, and FOXOs, ultimately resulting in cardiac hypertrophy." (PMID 32595507, 2020). "Therapeutic interventions such as resveratrol and metformin effectively attenuate cardiac hypertrophy by activating AMPK and inhibiting the mTOR pathway." (PMID 33328993, 2020). "Sprague-Dawley rats treated with supraphysiological doses of testosterone show eccentric cardiac hypertrophy mediated by ERK 1/2 and mTOR phosphorylation." (PMID 32849566, 2020). "Previous studies suggest that astragaloside IV corrects cardiac dysfunction and reduces myocardial hypertrophy by activating Nrf2/HO-1 pathway and PI3K/mTOR pathway and can promote angiogenesis." (PMID 32382301, 2020). "For example, treatment of a rat myocardial infarction model with LPA promoted cardiac hypertrophy which coincided with autophagic inhibition; furthermore, this was noted to occur via activation of the AKT/mTOR pathway." (PMID 32492043, 2020). "The mTOR and ERK1/2 signalling pathway is an important mediator of cardiac hypertrophy, and the observed changes in this pathway were alleviated by cordycepin treatment." (PMID 31225721, 2019). "Direct downregulation of p27 by miR-221 led to mTOR activation and diminished cardiac autophagy of diabetic OVE26 and/or Ang II-treated mice, resulting in cardiac hypertrophy." (PMID 30305865, 2018). "Overexpression of miR-99a attenuated cardiac hypertrophy in TAC mice and cellular hypertrophy in cardiomyocytes subjected to Ang II or isoprenaline (ISO) through suppression of expression of mTOR." (PMID 30305865, 2018). "To further clarify the molecular mechanisms involved in the regulation of autophagy in cardiac hypertrophy by Sestrin 1, we examined the effect of Sestrin 1 on AMPK/mTOR pathway." (PMID 28181410, 2017). "Here the authors show that two kinases, p38γ and p38δ, control heart growth by promoting mTOR activity via phosphorylation and consequent proteasome degradation of mTOR inhibitor DEPTOR, extending our knowledge of cardiac hypertrophy regulation." (PMID 26795633, 2016). "Overexpression of miR-99a attenuated cardiac hypertrophy in TAC mice and cellular hypertrophy in stimuli treated cardiomyocytes through down-regulation of expression of mammalian target of rapamycin (mTOR)." (PMID 26914935, 2016). "p38γ/δ promote cardiac hypertrophy by phosphorylating the mTORC1 and mTORC2 inhibitor DEPTOR, which leads to its degradation and mTOR activation." (PMID 26795633, 2016). "The downstream targets of AKT include GSK3β, mTOR,FOXO transcription factors and NFκB, all of which are involved in cardiac hypertrophy." (PMID 23349709, 2013). "Furthermore, circ-0001283 regulated autophagy and inhibited the PI3K/Akt/mTOR and ERK signaling pathways, potentially contributing to the pathogenesis of myocardial hypertrophy." (PMID 40007621, 2025). "In male Zucker diabetic fatty rat HFpEF models, dapagliflozin was found to reduce nitro-oxidative stress, pro-inflammatory cytokine levels, myocardial hypertrophy, and fibrosis, effectively preventing the onset of HFpEF through AMPK activation and inhibition of the mTOR pathway." (PMID 41169508, 2025). "Therefore, to further elucidate the molecular mechanism by which PGAM2 participates in the regulation of cardiac hypertrophy through HSP90, we examined the signaling pathways related to mTOR and IKKα." (PMID 39897023, 2025).
cardiac hypertrophy (continued). "Carboxypeptidase A4 (CPA4), a novel upstream regulator of mTOR, is significantly upregulated in isoprenaline (ISO)-induced cardiac hypertrophy in mice, promoting hypertrophy by enhancing PI3K-AKT signaling and activating mTOR and downstream S6K1 phosphorylation." (PMID 40002810, 2025). "Conversely, the mTOR signaling pathway was suppressed in Lztr1R409C/+ mice, and rapamycin treatment did not rescue LZTR1 mutation–dependent cardiac hypertrophy." (PMID 39352760, 2024). "Furthermore, in Rit1A57G/+ mice, a NS model of cardiac hypertrophy, the AKT/mTOR signaling pathway was activated in tissues from whole embryos and adult hearts under β-adrenergic stimulation." (PMID 39352760, 2024). "This activation influences key signaling pathways, including the mTOR-p70S6K, JNK, and TGF-β/Smad3, effectively reducing ISO-induced myocardial hypertrophy and fibrosis rat heart failure in vitro and in vivo models, and confirmed the targeting of 2-APQC in SIRT3 knockout mice." (PMID 38744811, 2024). "Herein, we found that USP38 positively regulates pathological cardiac hypertrophy and remodeling by preventing the proteasomal degradation of p-TBK1, leading to the activation of Akt-GSK3β/mTOR signaling pathway and the acceleration of heart failure progression." (PMID 38481817, 2024). "In conclusion, our present research showed that GPR30 activation by G1 could attenuate TAC-induced cardiac hypertrophy and fibrosis in OVX mice through regulating the autophagy of myocardial tissue by the Akt/mTOR pathway." (PMID 36674423, 2023). "Yu and colleagues reported that cardiac and circulatory expressions of irisin were increased in cardiac hypertrophy mice, and the treatment of irisin is able to inhibit pathological cardiac hypertrophy and fibrosis through AMPK-mammalian target of rapamycin (mTOR) signaling pathways." (PMID 36267573, 2022). "It was reported that puerarin prevented cardiac hypertrophy through regulating the AMPK, mTOR and Nrf2 pathway, suggesting that puerarin may be potential drug candidate for myocardial hypertrophy." (PMID 35402096, 2022). "First, this study effectively identified the mTOR signaling pathway as a potential target of testosterone-induced OVX SHR cardiac hypertrophy, but it did not explore mTOR upstream regulatory molecules." (PMID 34874016, 2022). "In addition, we examined phosphorylated mTOR and p70S6K, members of a key downstream signalling pathway of AMPK, in the progression of cardiac hypertrophy." (PMID 34953026, 2022). "Due to the crucial role of mTOR in cell survival and the diverse outcomes of its inactivation, mTOR would not be a good drug target for cardiac hypertrophy therapy." (PMID 34977198, 2021). "Besides, in the hypertrophic heart induced by ISO, the expression of SIRT6 was down-regulated, while the inhibition of mTOR restored cardiac function in muscle-specific SIRT6 knockout mice, which spontaneously developed into cardiac hypertrophy." (PMID 33855020, 2021). "In addition, SIRT1 is involved in cardiac angiogenesis in response to cardiac hypertrophy by regulating AKT activity, which subsequently affects mTOR activity." (PMID 33806509, 2021). "Moreover, a study reported that Iva prevented cardiac hypertrophy and fibrosis via inhibiting PI3K/AKT/mTOR pathway in an established transverse aortic constriction mouse model." (PMID 33975512, 2021). "Investigations have established dynamic phenomenon for AT1 R dependent transactivation of growth factor receptor-like EGF receptor (EGFR), followed by subsequent activation of Akt/p70S6, mechanistic target of rapamycin (mTOR), and Ras/ERK signaling resulting in cardiac hypertrophy and fibrosis." (PMID 34489714, 2021). "Cardiac hypertrophy in neonatal LOI mice is mediated by circulating IGF2 activation of AKT/mTOR signaling in cardiomyocytes and is independent of H19 gene function." (PMID 34402430, 2021).
cardiac hypertrophy (continued). "In addition, hypoxia-induced increases in PAP, cardiac hypertrophy, and lung expression of the proteins PI3K/Akt/mTOR/autophagy pathway were partially reversed by treatment with LY294002." (PMID 32508639, 2020). "Moreover, pharmacological inhibition of mTOR restored cardiac function in muscle-specific SIRT6 knockout mice, which spontaneously develop cardiac hypertrophy." (PMID 31372634, 2019). "Considering the important roles of growth promotion by the mTOR/P70S6K/S6 signaling axis, it is plausible to reason that chronic βAR activation may lead to cardiac hypertrophy via this signaling pathway." (PMID 22028912, 2011). "It is believed that GSK-3 inhibition induced-cardiac hypertrophy is independent of the mTOR pathway." (PMID 22028912, 2011). "The findings indicate that GLP-1 RA regulates the expression of Ang II/AT1R/ACE2 and activates the AMPK/mTOR pathway, thereby preventing cardiac hypertrophy, suggesting that GLP-1 agonists could be a useful treatment for patients with pathologic cardiac hypertrophy." (PMID 38673991, 2024). "miR-4732-3p might also impact cardiac hypertrophy by targeting genes such as PI3K/Akt and mTOR." (PMID 39595980, 2024). "Furthermore, signal transduction validation in vivo and in vitro demonstrated that Trim44 deficiency in the myocardium inhibited the activation of cascade pathways involved in cardiac hypertrophy, AKT/mTOR/GSK3β/P70S6K, especially response to pathological stress." (PMID 35855640, 2023). "In cardiac hypertrophy, the PI3K-Akt signaling pathway is activated by many types of cellular stimuli or toxic insults to regulate fundamental cellular processes including protein synthesis, proliferation, and survival, via its downstream signals, such as AKT, GSK3β, mTOR, P70S6K, and eIF-4E." (PMID 36704572, 2023). "In conclusion, for the first time, we showed that DBZ robustly protects against cardiac hypertrophy in rats after TAC surgery and in cardiomyocytes treated with Ang II, which is mostly due to the antioxidant and anti-ER stress properties of DBZ, via the mTOR/GSK3β(Ser9)/β-TrcP/NRF2 pathway." (PMID 35185583, 2022). "In addition, we investigated whether TQ affects the mammalian target of rapamycin (mTOR) and its effector p70S6K, members of a key downstream signalling pathway of AMPK in the progression of cardiac hypertrophy." (PMID 34953026, 2022). "Although our study suggested that the antioxidative effects of DBZ in stress-induced cardiac hypertrophy are mTOR/β-TrCP/NRF2 pathway-dependent, it may not be the only mechanism to benefit cardiac hypertrophy." (PMID 35185583, 2022). "Moreover, it has been suggested that AMPK activation prevents cardiac hypertrophy independent of mTOR by inhibiting microtubule accumulation or by O-GlcNAcylation of structural proteins." (PMID 33546773, 2021). "Overexpression of miR-99a attenuates cardiac hypertrophy in transverse aortic constriction (TAC) mice and in isoprenaline (ISO)/angiotensin-II (Ang II)-induced hypertrophic cardiomyocytes through downregulation of hypertrophic mammalian target of rapamycin (mTOR) signaling pathway." (PMID 34527667, 2021). "MiR-200a-3p accelerated cardiac hypertrophy by directly modulating WDR1 and simultaneously regulating PTEN/PI3K/AKT/CREB/WDR1 pathway, while the miR302-367 cluster was found to impair autophagy to worsen cardiac hypertrophy through silencing PTEN and consequently activating PI3K/AKT/mTOR pathway." (PMID 33195446, 2020). "Therefore, we identified CPA4 as a new upstream regulator of the mTOR pathway and CPA4 may serve as a potential therapeutic target for cardiac hypertrophy." (PMID 32347291, 2020). "Our results demonstrated that FKBP12.6 protects heart from AngII‐induced cardiac hypertrophy through preventing the activations of the Ca2+/calmodulin‐dependent signalling pathways such as calcineurin/NFATc4, CaMKII/MEF‐2, AKT/GSK3β/NFATc4 and AKT/mTOR pathways." (PMID 29682889, 2018).
cardiac hypertrophy (continued). "However, in ZDF-M with prolonged hyperglycemia and a short term hyperinsulinemia (due to pancreatic beta cell burn-out), neither cardiac hypertrophy nor mTOR activation are seen due to muscle wasting in response to severe DM, yet, they exhibit fibrosis." (PMID 29259233, 2017). "This study reveals the existence of cross-talk mechanisms between TR3 and the TSC that function in the regulation of mTOR signalling and demonstrates a novel physiological function for TR3 that may qualify it as a clinical target for the treatment of cardiac hypertrophy." (PMID 23197407, 2013). "Therefore, this study provides insight into the mechanism by which TR3 regulates AngII-induced pathological hypertrophy through its influence on mTOR signalling and reveals that TR3 may be a unique target for the treatment of clinical cardiac hypertrophy." (PMID 23197407, 2013). "Mice lacking ACSL1 specifically in adipose tissue have defects in adipose FFA oxidation, whereas those unable to express ACSL1 in heart ventricles show compensatory catabolism of glucose and amino acids leading to mTOR activation and cardiac hypertrophy without lipid accumulation or dysfunction." (PMID 22829935, 2012). "In addition, the addition of the SIRT3 inhibitor nicotinamide increased the expression levels of p-Akt and p-mTOR, which were decreased by 2-APQC, suggesting that 2-APQC may inhibit the development of myocardial hypertrophy by activating the SIRT3-regulated Akt/mTOR signaling pathway." (PMID 38744811, 2024). "In addition, NRF2 knockdown did not impair the downregulation of mTOR phosphorylation by DBZ in Ang II-stimulated NRCMs, suggesting that mTOR acted upstream of NRF2 in Ang II-induced cardiac hypertrophy." (PMID 35185583, 2022).
leukemia (301 papers, 2007 to 2026). A malignant (clonal) hematologic disorder, involving hematopoietic stem cells and characterized by the presence of primitive or atypical myeloid or lymphoid cells in the bone marrow and the blood. "In FA− deficient bone marrow, fetal stem cell exhaustion and leukemogenesis have been linked to elevated protein synthesis, underscoring the potential for mTOR sensitization in FA− deficient leukemia." (PMID 40805278, 2025). "The AKT/mTOR axis plays a key role in leukemogenesis as demonstrated in a mouse model of leukemia induced by Pten-loss, in which mTORC1 deletion resulted in a significant increase in survival." (PMID 37775560, 2023). "The activation of the mTOR pathway was confirmed in Kmt2d‐deficient leukemia cells, as shown by Western blots with antiphosphorylated ribosomal protein S6, a substrate of direct mTORC1 target S6K1." (PMID 37142882, 2023). "Upregulation of the PI3K/AKT/mTOR pathway results in the development of high-risk leukemia that is resistant to chemotherapy." (PMID 33531656, 2021). "DNMT3A mutation in mice promotes the development of leukemia by upregulating CDK1 through the mTOR pathway." (PMID 34093541, 2021). "mTOR inhibition alone was shown to decrease leukemia growth in a preclinical model of high-risk ALL characterized by early relapse." (PMID 32235787, 2020). "Several of these clinical studies are evaluating the benefit of PI3K/AKT/mTOR inhibition in association with immune checkpoint inhibitors in patients with colorectal, lung, leukemia, or other solid tumors." (PMID 31500143, 2019). "The mTOR control over the metabolic phenotype has been associated with the resistance of leukemia cells to various agents." (PMID 30110936, 2018). "To conclude, leukemia cells that are susceptible or resistant to PI3K-Akt-mTOR inhibitors differ in energy, amino acid, and arachidonic acid metabolism, and modulation of arachidonic acid metabolism alters the activation of mTOR and its downstream mediators." (PMID 29382066, 2018). "Specifically, FKBP51 is associated with the mTOR pathway to enhance the activation of NF-κB and increase drug-induced apoptosis in leukemia." (PMID 29587629, 2018). "Metformin represents an interesting opportunity to target leukemia through inhibition of constitutive mTOR, a pathological hallmark in leukemogenesis." (PMID 30147674, 2018). "It has been shown that a number of genetic mutations elevate PI3K/AKT/mTOR signaling, and contribute to cell proliferation, survival, and drug resistance in leukemia." (PMID 28186963, 2017). "Taken together, TTLshort/high-risk leukemias are characterized by highly activated constitutive mTOR signaling maintained upon ex vivo culture, in contrast to low and decreasing mTOR activity in TTLlong ALL." (PMID 25682198, 2015). "Gene expression profiling identified genes coding for molecules involved in mTOR signaling to be associated with TTLshort/early relapse leukemia." (PMID 25682198, 2015). "The important role of mTOR and its inhibition was further reinforced, when deficiency of Raptor, an essential part of mTORC1, induced eradication of leukemia in a murine model of T-ALL." (PMID 26056603, 2015). "In line, we observed significantly postponed leukemia reoccurrence upon rapamycin treatment in animals engrafted with TTLshort leukemias indicating in vivo effectivity on mTOR driven TTLshort/high-risk ALL." (PMID 25682198, 2015). "We showed that hyperactivated mTOR signaling can be efficiently repressed, identifying a therapeutic target in these high-risk leukemias." (PMID 25682198, 2015). "Therapeutically, rapamycin mediated inhibition of mTOR resulted in loss of leukemia-initiating stem cells and gain of normal hematopoietic stem cells in leukemia." (PMID 25749036, 2015). "In this study we now investigate the functional activity of this key survival pathway and evaluate mTOR as a molecular target for directed therapy in high-risk leukemia ex vivo and in a preclinical model setting in vivo." (PMID 25682198, 2015).